ZEB1 (zinc finger E-box binding homeobox 1)
Diseases named in the same sentence as ZEB1 in open-access papers (continued):
Sharing a sentence is not in itself a finding about the gene and the disease.
tumor (continued). "Given that IFNγ activates ZEB1, future studies are motivated to address if the metastatic potential of UM is triggered by such soluble inflammatory factors or if a single critical factor could independently trigger an unique intrinsic signaling pathway downstream of 4-1BBL expressed on tumor cells." (PMID 38191418, 2024). "EMT-induced transcription factors like Snail, Zeb1, and Twist have been shown to regulate and promote EMT, thereby contributing to tumor cell metastasis." (PMID 38469234, 2024). "It has been demonstrated that ZEB1 can indirectly promote the expression of VEGF by inhibiting miR-200b, and then promote the generation of tumor NV." (PMID 38822380, 2024). "This study uncovered that the E3 ubiquitin ligase activity of TRIM26 was previously shown to target ZEB1, an oncoprotein crucial for the development of HCC and thus to act as a tumor suppressor in HCC." (PMID 38260302, 2024). "Like ZEB1, TGIF1 was a potential hypermethylated biomarker identified in another tumor tissue type in this analysis." (PMID 38886487, 2024). "For example, EVs that are derived from M2 macrophages carry the long noncoding RNA NEAT1 sponge miR-101-3p, which upregulates the transcription factor zinc finger E-box-binding homeobox 1 (ZEB1), thereby promoting PD-L1 expression by tumor cells." (PMID 39528800, 2024). "ZEB1, as an EMT enhancer and miR-200 transcriptional agent, relieves miR-200 suppression of PD-L1 on tumor cells, resulting in immunosuppression of CD8+ T cells and metastasis." (PMID 38462658, 2024). "Zinc Finger E-Box Binding Homeobox 1 (ZEB1), a target of miR-431, plays a role in reversing epithelial–mesenchymal transition (EMT), enhancing the tumor’s response to therapies." (PMID 39682247, 2024). "The collaborative action of the ZEB1/NuRD complex transcriptionally represses the tumor suppressor gene CLDN7, stimulates glycolysis, and facilitates tumor progression." (PMID 39193340, 2024). "It has been shown that ZEB1, which is a transcription factor involved in EMT, has an imperative role in facilitating cell migration and invasion during tumor metastasis." (PMID 39196911, 2024). "This heightened expression was particularly pronounced at the invasive front, suggesting a potential correlation between ZEB1 and CD73 in the context of tumor invasiveness." (PMID 38388432, 2024). "Combined expression of WNT ligands (WNT3A, WNT4, WNT7B, WNT9A, WNT10A, WNT11) in BRCA patient tumours has a positive correlation (R = 0.27, p value = 0) with the combined expression of key EMT-inducing transcription factors SNAI1, SNAI2, ZEB1, ZEB2 and TWIST1." (PMID 38678032, 2024). "miR-205 disrupts ZEB1/2-mediated EMT109 and inhibits tumor development from the basal membrane to the stroma." (PMID 37692482, 2024). "The upregulation of ZEB1 also partially reversed the impact of USP22 silencing on the phenotypes of OC cells, indicating that USP22 promotes tumor progression by upregulating ZEB1." (PMID 39530604, 2024). "As such, inhibition of PAK4 reduces expression of Slug and Zeb-1, upregulating expression of VCAM-1 and Claudin-14 in tumor ECs, which eventually enhances T cell adhesion and improves CAR T cell immunotherapy." (PMID 38580870, 2024). "Regarding the expression of transcription factor genes, the expression was higher in EPCAM-positive CTCs (CDH1, ZEB1, ZEB2) and in EPCAM-positive primary tumor cells (CDH1, SNAIL1, SNAIL2, ZEB2) compared to EPCAM-negative CTCs and tumor cells." (PMID 39456890, 2024). "Zinc finger E-box binding homeobox 1 (ZEB1), a transcription factor, plays an important role in drug resistance by inducing the EMT process, leading to tumor invasion and metastasis." (PMID 38927885, 2024). "These cell-intrinsic signaling pathways cooperate to induce the transcriptional activation of EMT-TFs, such as SNAIL, ZEB1/2, and Twist1/2, subsequently triggering the EMT process for induction of the transition to the mesenchymal state of the tumor cells." (PMID 38792011, 2024).
tumor (continued). "It is known that microRNA-200 family miRNAs target genes ZEB1 and ZEB2, which both are involved in EMT and tumour metastasis." (PMID 37705830, 2023). "ZEB1 is a critical activator of EMT, which upregulates tumor cell plasticity and EMT to acquire cancer stem cell properties." (PMID 37810976, 2023). "Conversely, tumour cells in the mesenchymal state possessed low expression levels of GRHL2 and OVOL1, high expression levels of ZEB1 and SNAI2." (PMID 36808651, 2023). "Several factors mediate ZEBs; for example, the activation of MEK1/2, ERK1/2, Fos-related antigen 1 (Fra-1), and TGF-β enhance the expression of both ZEB1 and ZEB2, increasing tumor invasion." (PMID 37444447, 2023). "High ZEB1, PD-L1, TIMP2, TWIST1, and VIM expression represents a specific gene signature in blood-circulating tumor cells from NMIBC patients." (PMID 37627900, 2023). "Moreover, in bevacizumab and sorafenib resistant tumor cells, the expression of ZEB1 is increased, and tumors show stronger invasion and metastasis ability, suggesting that ZEB1 may play an important role in the process of resistance to anti-angiogenesis therapy." (PMID 36906615, 2023). "EMT-transcription factors (EMT-TFs) ZEB1 and SNAIL function as master genetic and epigenetic regulators of this tumor-intrinsic effect." (PMID 37398248, 2023). "Tumour cells in a hybrid E/M state possessed moderated expression levels of GRHL2, OVOL1, ZEB1 and SNAI2." (PMID 36808651, 2023). "In circulating tumor cells and in patient tumor biopsies, too, expression levels of ELF3 and ZEB1 were anti-correlated." (PMID 36864480, 2023). "E-cadherin, Vimentin, N-cadherin, Fibronectin, Snail, Slug, Twist, and ZEB1 are crucial biomarkers and regulators of EMT, an important initial step of tumor metastasis." (PMID 37283789, 2023). "In bladder cancer tissue samples and cell lines, ZEB1 was a target gene of linc-ROR, promoting tumor cell proliferation and inhibition of cell apoptosis." (PMID 36827545, 2023). "New evidence reveals that ZEB1 drives EMT and thus advances tumor invasion and metastasis by initiating stem cell features, immune evasion, and epigenetic reprogramming." (PMID 37827696, 2023). "The transcription factors ZEB1 and ZEB2 are significantly downregulated in all cell lines compared to tumor tissue." (PMID 37345150, 2023). "The results showed that E-cadherin mRNA in shHOTAIR SKOV3 cells from injected tumor-bearing mice was higher than that in control cells, while the TGF-β1 and zeb1 expression was lower than that in control SKOV3 cells." (PMID 38070058, 2023). "ZEB1 is an essential transcription factor in epithelial-mesenchymal transition (EMT), which is involved in embryonic development, fibrosis, and tumor progression, among other biological processes." (PMID 36824454, 2023). "The Transwell/ Boyden chamber migration assay data indicated a reduced migratory activity of the M13HS ZEB1-knock-out tumor hybrids, whereas in scratch/ wound-healing assays only the M13SH-8 ZEB1-knock-out cells possessed a reduced locomotory activity." (PMID 38139138, 2023). "After treatment with SP600125, an inhibitor for JNK signaling, the expression of E-cad, Vim, ZEB1 and Snail mediated by FAM3C was reversed, suggesting that FAM3C promotes tumor cell EMT via JNK-ZEB1/Snail signaling activation." (PMID 37056931, 2023). "Interestingly, when the authors introduced a double knockout of Zeb2 and Zeb1 in this same MLL-AF9 model they did not observe any further delay in tumor onset suggesting that Zeb1 loss was could not compound the effect of Zeb2 loss alone." (PMID 37600794, 2023). "To this end, we assessed by Western blot the protein expression of several markers known to regulate tumour proliferation and invasion, such as Cyclin D3, CDK 2/4/6, TCF 1/7, Integrin beta-1, MT1-MMP, SNAIL, Vimentin, ZEB1, and ZO-1." (PMID 37887342, 2023).
tumor (continued). "Zinc finger E-box binding homeobox 1 (ZEB1), a key transcription factor regulating EMT, inhibits the expression of miR-200, so miR-200 is usually at a low level in the tumor microenvironment." (PMID 37275876, 2023). "The IHC results of xenografted tumor showed that USP33 depletion inhibited the expression of Ki67, PCNA, TGFBR2 and ZEB1." (PMID 37322017, 2023). "To further understand the cellular origin of this increased EMT marker expression, we conducted IHC for EPCAM to stain tumor epithelium as well as VIM and ZEB1 in murine and human samples." (PMID 38153787, 2023). "For example, the proliferation index in tumor cells was high (40–50% Ki-67 and PCNA positivity), and staining for ZEB1 was low (although ZEB1 was easily detected in nearby stromal cells with mesenchymal differentiation)." (PMID 37349501, 2023). "The PI3K/Akt pathway targets GSK3β/β–catenin to regulate ZEB1 transcription and subsequently regulates the expression of cytokeratins, vimentin, and MMP2 for tumor cell adhesion, invasion, and migration." (PMID 37627900, 2023). "And, TRIM58 interacted with ZEB1 to facilitate ZEB1 protein degradation via UPP, which resulted in the exacerbation of NSCLC tumor expansion, invasion, and metastasis." (PMID 36644609, 2023). "The expression of ZEB1/2 in epithelial cells induces EMT and promotes a mesenchymal phenotype, thereby facilitating tumor invasion and metastatic dissemination into a cancer stem cell state." (PMID 37444447, 2023). "The tumour cells in the epithelial state possessed elevated expression levels of GRHL2 and OVOL1, low expression levels of ZEB1 and SNAI2." (PMID 36808651, 2023). "Taken together, our study has demonstrated that USP22 is a novel co-regulator of ZEB1 to enhance ZEB1-induced VEGFA transcription via USP22 deubiquitination activity, thereby promoting tumor growth/invasion/VM formation and angiogenesis in HCC." (PMID 36906615, 2023). "Upregulation of EMT transcription factors, such as TWIST1, ZEB1/2 and SNAI1/2 have been reported to promote migration and invasion of tumor cells in many types of tumors." (PMID 35205125, 2022). "We knocked out Tgfβr2 in p18−/−; Brca1MGKO tumor cells and found that Tgfβr2 KO led to lower expression of the EMT markers Vim, Fn, Snail, Zeb1, Slug, and higher expression of the epithelial markers including Cdh1 and Epcam." (PMID 35236825, 2022). "The miR-200 family members (miR-200a, -200b, -200c, -141, -429) directly targets the zinc-finger E-box-binding homeobox 1 (ZEB1), a transcription activator of EMT, resulting in inhibition of metastasis and invasion of tumor cells." (PMID 36230658, 2022). "The role of miR-200 has previously been reported as a tumor suppressor factor for the inhibition of the EMT process and tumor growth of GC through targeting ZEB1 and ZEB2." (PMID 34923813, 2022). "To this end, we compared protein levels of E-Cadherin, Vimentin, N-Cadherin, ZEB1 and SLUG in paired normal mucosa/tumor samples derived from L5, L6 and L7 patients." (PMID 35837106, 2022). "In GBM, WNT/β-catenin signaling is activated and promotes tumor invasion by inducing expression of downstream EMT transcription factors like Twist, ZEB1, and Snail." (PMID 36386155, 2022). "The expression of circ-ZEB1 was markedly correlated with venous invasion, TNM stage, and tumor size." (PMID 35277182, 2022). "The miR-200 family represses EMT and tumor invasion by targeting the 3′UTRs of major drivers of EMT, including TGFB, ZEB1 and ZNF217." (PMID 36551531, 2022). "We have previously reported that the EMT-TFs SNAI1 and ZEB1 are involved in the direct overexpression of the programmed cell death protein ligand-1 (PD-L1) and the macrophage immune checkpoint CD47 on tumor cells." (PMID 36465484, 2022).
tumor (continued). "Moreover, based on the expression of EMT hallmark genes including SNAI2, N-cadherin, Vimentin, ZEB1, ZEB2, SNAI1, Fibronectin, TWIST1 and E-cadherin, we found that patients with high risk score distinctly exhibited a mesenchymal phenotype, suggesting a higher tumor malignancy." (PMID 36505846, 2022). "We found that the expression of epithelial marker E-cadherin was downregulated, while the expression of mesenchymal markers, including ZEB-1, Vimentin, Slug and α-SMA, were upregulated, indicating the enhanced EMT in tumor issuses pretreated with ISO." (PMID 35517411, 2022). "The resistant cells showed more pronounced expression of EMT markers, such as ZEB1, Slug, and N-cadherin, and drug-resistant markers, such as MDR1 and cathepsin L, mimicking an advanced tumor signaling circuit." (PMID 36291907, 2022). "Under-expressed OGN and EFS, compared to the normal samples, improved survival, reduced tumor recurrence, and reversed the epithelial to mesenchymal transition by inhibiting EGFR/AKT/Zeb-1 in tumors." (PMID 35741697, 2022). "Positive correlation was also found between ZEB1 and TIM-3, as well as CD8 and the following markers: PD-1, PD-L1+ tumour cells, CD163, and LAG-3." (PMID 36358805, 2022). "Endothelial ZEB1 deletion in tumor-bearing mice diminishes tumor angiogenesis and reduces TGF-β activity, thus reducing tumor growth and metastasis." (PMID 35454770, 2022). "DYRK1A was found to be coexpressed with several STAT3 target genes, including zinc finger E-box-binding homeobox 1, VEGFA and heat shock protein 90, in clinical tumour samples from patients with HCC." (PMID 35655269, 2022). "ZEB1 (also named TCF8 or DeltaEF1) is a zinc finger E-box binding homeobox 1, transcription factor that promotes tumor invasion and metastasis by inducing EMT." (PMID 36250005, 2022). "Expression of both ZEB1 and ZEB2 was differential in OvCa samples (TCGA vs. GEO, p < 0.05) and present in all analyzed tumor and normal tissues." (PMID 35163224, 2022). "ZEB1, snail, CD44, and OCT4 have been reported in the literature to be involved in tumour de-differentiation, therefore it is plausible that this mechanism occurs in the tumour core, which is more often hypoxic and hosts stem cell niches." (PMID 36358805, 2022). "Consistent with this, treatment with sorafenib, a RAF/ERK inhibitor, significantly decreased tumor weight and expression of RAF1 and ZEB1, a downstream effector of the RAF/ERK pathway, in HHUA-SP-derived tumors but not non-SP-derived tumors." (PMID 35659728, 2022). "For instance, the lncRNA antisense to ZEB1 (ZEB1-AS1) can interact with MLL1 and recruit it to the promoter region of ZEB1 to epigenetically induce ZEB1 transcription, promoting EMT and tumor metastasis." (PMID 36114510, 2022). "This is consistent with previous studies linking ZEB1, SNAI1 and TWIST1 with a mesenchymal phenotype of tumor cells in CRC." (PMID 35565409, 2022). "In particular, it serves as a tumor suppressor in diverse malignancies by targeting critical oncogenes or anti-oncogenes, including EZH2, DNMT3a, MALAT-1, ZEB1, and USP47." (PMID 35205710, 2022). "Altogether, a signaling axis consisting of lncRNA-ATB/miR-200c/ZNF217/TGF-β2/ZEB1 participates in EMT and tumor progression." (PMID 36551531, 2022). "Zinc finger E-box binding homeobox 1 (ZEB1) is another transcription factor expressed by CAFs in CCA cells that promotes mesenchymal transition and stemness in tumor cells." (PMID 36362726, 2022). "Particularly, miR-217 induces tumor suppression by targeting downstream genes such as astrocyte elevated gene-1 (AEG-1), mitogen-activated protein kinase (MAPK), and zinc finger E-box binding homeobox 1 (ZEB1)." (PMID 35814444, 2022). "The Mes tumor subtype predominantly expresses fibroblastic/mesenchymal genes, such as PDGFRA, VCAM1, ZEB1, TWIST1; and extracellular matrix genes, including collagen and FN1 (bolded genes are overlapping with our negative prognostic signature)." (PMID 36555638, 2022).
tumor (continued). "Expression levels of ZEB1, YAP1, CCND1, and BCL2 were consistent with the database analysis and demonstrated significantly high values in tumor tissues (logFC ≥ 1.5)." (PMID 35453574, 2022). "Circ-ZEB1 knockdown has been shown to reduce TNBC cell proliferation and tumor formation by releasing miR-448 and consequently decreasing the expression of the miR-448 target, eEF2K." (PMID 35865469, 2022). "ZEB1 is known to play pleiotropic roles in cancer, including promoting EMT by repression of CDH1 to make tumor cells mobile and invasive, and by enhancing cell proliferation by repression of cyclin-dependent kinase (CDK) inhibitor genes such as P15 and P21." (PMID 35404029, 2022). "This tumor and EMT inducive role of Six1 seems to be through increased levels of ZEB1, SNAIL1, and TWIST1." (PMID 37305018, 2022). "A similar mutually inhibitory loop exists between miR-1199-5p and Zeb1, coordinating EMT and tumor metastasis." (PMID 36114510, 2022). "miR-200c acts as a tumor suppressor that inhibits tumor growth and blocks EMT by targeting ZEB1 and ZEB2." (PMID 35406505, 2022). "The sequence of miR-203a-3p is complementary to conservative sites of 3′-UTRs of ZEB1 and ZEB2 that suggests miR-203a-3p to be a tumor suppressor." (PMID 35163224, 2022). "Since abnormal activation of EMT is an important biological process in tumor progression, we examined the EMT-related markers ZEB1, E-cadherin, N-cadherin and Vimentin in GC cells." (PMID 35295342, 2022). "Several sets, including those for cell migration, ZEB1 targets, EGFR signaling, lin genes silenced by the tumor microenvironment, and CDH1 targets, were all closely linked to cancer." (PMID 35645615, 2022). "The antagonistic effect of IL-24 on ZEB1 leads to a suppression of GBM cell migration and invasion as well as an enhancement of the chemosensitivity of tumor cells to TMZ." (PMID 36402997, 2022). "Intriguingly, ZEB1, a transcriptional repressor, inhibits E-cadherin transcription by recruiting BRG1 and promotes the epithelial–mesenchymal transition (EMT) and tumor progression." (PMID 36494341, 2022). "This event leads to the activation of HIF‐1α, which transcribes ZEB1 and Twist to induce EMT and promote tumor metastasis." (PMID 35601657, 2022). "On the contrary, miRNAs-200c and 205 appeared as downregulated in OSCC cell lines and tumour samples (the former) and in OSCC cell lines (the latter), whereas their targets, ZEB1 (for miRNA-200c) and ZEB1 and ZEB2 (for miRNA-205), showed to be upregulated." (PMID 34564679, 2022). "For example, targeting and suppressing ZEB1 with the HDAC1-specific inhibitor mocetinostat or through the expression of miR-200 sensitizes resistant cancer cells to MEK inhibitors and reduces tumor growth in vivo." (PMID 35454770, 2022). "In contrast, ID3 + cells highly expressed genes such as MDK, ZEB1, and LGR5 that play important roles in tumor stemness." (PMID 35347134, 2022). "Thus, in summary, in this study we have shown that miR-449a could be considered as a tumor suppressive miRNA in ER + tumors, and that miR-200c, which targets ZEB1 and ZEB2 (major regulators of EMT) can reverse EMT in our cell line pII an ER-acquired resistance cell line." (PMID 35879960, 2022). "A major difference between differentiated and classical pathway of cSCC progression is the aggressiveness of the arising tumors as well as the point during the progression where tumor cells displaying advanced EMT markers (Vimentin, Zeb1) can be observed." (PMID 35666359, 2022). "FAT1 is frequently inactivated resulting in increased tumor stemness and metastasis in a mouse model of SCC involving CAMK2, CD44, and SRC activities that induce nuclear translocation of YAP1 and ZEB1." (PMID 34459003, 2021).